MTSS1 (MTSS I-BAR domain containing 1)
Diseases named in the same sentence as MTSS1 in open-access papers (continued):
Sharing a sentence is not in itself a finding about the gene and the disease.
cancer (continued). "In summary, downregulation of MTSS1 increases the resistance of AML cells not only to standard AML therapeutics, but to members of several different classes of anti-cancer drugs." (PMID 33782537, 2021). "Here, we experimentally characterise the expression levels of MTSS1 in CLL and show an interesting heterogeneous expression pattern in different stages of cancer." (PMID 30858428, 2019). "Other reported targets of the miR-23a, whose suppression facilitated the cancer cell migration and invasion, include XIAP, metastasis suppressor protein 1 (MTSS1), insulin receptor substrate 1 (IRS-1), Sprouty homolog 2 (SPRY2), and PTEN." (PMID 30577536, 2018). "Down-regulation of MTSS1 expression was observed both in oesophageal tumour tissues and ESCC cancer cell lines." (PMID 21696600, 2011). "Twenty of these genes are located in 8q22–q24 and 17q21, including PAPBC1, RAD21, ATAD2, MTSS1, SQLE, ST3GAL1, C17orf37, ABCC3 and PTPN2, previously reported as cancer-related genes." (PMID 21339811, 2011). "miR-23a-3p has an oncogenic role in these types of cancer, with direct targeting of PGC-1α and G6PC, MTSS1, and RKIP, as well as suppressor genes of both the Wnt/β-catenin signaling pathway and DNA methylation pathway in cooperation with other miRNAs in the miR-23a/24/27a cluster." (PMID 38397007, 2024). "Several mechanisms, including DNA-methylation, have been proposed to explain why MTSS1 is downregulated in cancers, and sometimes not at all expressed in metastases." (PMID 37920825, 2023). "Interaction between MTSS1 and AIP4 was also observed in cancer cells." (PMID 36810288, 2023). "An I-BAR domain protein, MIM (missing in metastasis, also known as MTSS1), suppresses metastasis by regulating cytoskeletal dynamics and lamellipodia formation, consequently affecting the invasion and metastatic behaviour of cancer cells." (PMID 37132654, 2023). "MTSS1 is expressed in most normal tissues and a few nonmetastatic cancer cell types, but its expression is significantly reduced or even absent in many metastatic tumors." (PMID 32913477, 2020). "While a number of different studies have begun the process of characterizing the function of MTSS1 in a variety of cancer models, to our best knowledge, no functional characterization has been performed for MTSS1 in PDAC." (PMID 28146435, 2017). "It is evident from the present study that MTSS1 was absent only in a poorly differentiated cell line, but was maintained in the well or moderate differentiated cell lines, which indicated that MTSS1 expression may be associated with more aggressive cell lines within the same type of cancer." (PMID 21696600, 2011). "Our study has shown a reduced or absent levels of MTSS1 both in oesophageal squamous cell carcinoma tumour tissues and cancer cell line." (PMID 21696600, 2011). "This study showed that MTSS1 could be of value as a potential prognostic indicator in human ESCC and may be an important target for cancer therapy." (PMID 21696600, 2011). "MTSS1 serves as a potential prognostic indicator in human ESCC and may be an important target for cancer therapy." (PMID 21696600, 2011). "Additionally, our study demonstrates the correlation of MTSS1 expression with ICB efficacy and discovers a combinatory approach to improve ICB response, and thus may have important implications on cancer therapy." (PMID 36810288, 2023). "Although we have some understanding of the role of MTSS1 in cancer, cellular pathways that may regulate its function are not well-known." (PMID 29497041, 2018). "Despite evidence showing that MTSS1 could be important for regulating metastasis in many different cancers, its function in PDAC has not been studied." (PMID 28146435, 2017). "However, it remains to be determined whether in addition to elevated β-TRCP expression, cancer cells also exhibit increased CKI activity, resulting in increased degradation of MTSS1." (PMID 24318128, 2013).
cancer (continued). "Notably, compared to wild-type MTSS1 and empty vector expressing cells, S322A-MTSS1 expressing prostate (PC3) and breast (MDA-MB-231) cancer cells exhibited a significant reduction in cell migration and subsequently, reduced ability in recovering from scarring." (PMID 24318128, 2013). "Since the study of MTSS1 has been restricted to a limited number of cancer types and available data seem to be controversial, whether or not MTSS1 serves as a metastasis suppressor has not been clearly defined to date." (PMID 21696600, 2011). "Although metastasis suppressor 1 (MTSS1) may be a critical regulator of carcinogenesis in different cancers, study of MTSS1 has been mainly restricted to several cancers and available data seem to be controversial, leaving the involvement of MTSS1 in cancer not clearly defined." (PMID 20712855, 2010). "Certainly, MTSS1 and TIAM1 were almost absent in G10 cells, as described in metastatic and poor prognosis cancers." (PMID 27206673, 2016).
blood cancers (1 paper, 2019). "For this reason, we were interested to investigate the expression levels of MTSS1 in blood cancers, especially of B and T cell origin." (PMID 30858428, 2019).
infection (1 paper, 2013). The state of being infected such as from the introduction of a foreign agent such as serum, vaccine, antigenic substance or organism. "To further examine this hypothesis, we depleted endogenous Cullin 1 or β-TRCP via lentiviral shRNA infection to examine its effects on MTSS1 abundance." (PMID 24318128, 2013).
MTSS1 also shares sentences with these, for which no sentence is quoted: atrial fibrillation (2 papers); chronic lymphocytic leukaemia (2); neuroblastoma (2); Anxiety (1); bacterial infections (1); bladder tumor (1); cervical (1); colon cancer (1); coronary artery disease (1); dilated cardiomyopathy (1); gastric adenocarcinoma (1); heart failure (1); hematological malignancies (1); hematopoietic cancers (1); hypertrophic cardiomyopathy (1); intracerebral hemorrhage (1); kidney cancer (1); leukopenia (1); liver cirrhosis (1); Lymphatic Metastasis (1); manic episodes (1); mantle cell lymphoma (1); metastatic prostate carcinoma (1); migraine (1); multiple sclerosis (1); neurological diseases (1); non-small cell lung carcinoma (1); prostate tumor (1); psoriasis (1); renal carcinoma (1).
A further 5 diseases each share a sentence with MTSS1 in 1 paper.